DDX20 (DEAD-box helicase 20)
Description:
The SMN complex catalyzes the assembly of small nuclear ribonucleoproteins (snRNPs), the building blocks of the spliceosome, and thereby plays an important role in the splicing of cellular pre-mRNAs. Most spliceosomal snRNPs contain a common set of Sm proteins SNRPB, SNRPD1, SNRPD2, SNRPD3, SNRPE, SNRPF and SNRPG that assemble in a heptameric protein ring on the Sm site of the small nuclear RNA to form the core snRNP (Sm core). In the cytosol, the Sm proteins SNRPD1, SNRPD2, SNRPE, SNRPF and SNRPG are trapped in an inactive 6S pICln-Sm complex by the chaperone CLNS1A that controls the assembly of the core snRNP. To assemble core snRNPs, the SMN complex accepts the trapped 5Sm proteins from CLNS1A forming an intermediate. Binding of snRNA inside 5Sm triggers eviction of the SMN complex, thereby allowing binding of SNRPD3 and SNRPB to complete assembly of the core snRNP. May also play a role in the metabolism of small nucleolar ribonucleoprotein (snoRNPs).
Synonyms: DP103; GEMIN3
Tractability: Small molecule: a structure with a bound ligand is known. PROTAC: ubiquitination databases record sites on it; its protein half-life has been measured.
Target class: Enzyme; Hydrolase
Gene: Protein-coding gene on chromosome 1 (111,754,832 to 111,775,602, forward strand). Ensembl gene ENSG00000064703.
Subcellular location: Cytoplasm; Nucleus, gem
Subcellular location (Human Protein Atlas): Nuclear bodies; Cytosol; Nucleoplasm
Pathways (Reactome):
Disease: SARS-CoV-2 modulates host translation machinery
Metabolism of RNA: snRNP Assembly
Gene Ontology:
Molecular function: ATP hydrolysis activity; DNA-binding transcription factor binding; protein binding; ribonucleoside triphosphate phosphatase activity; RNA helicase activity; ATP binding; histone deacetylase binding; nucleic acid binding; protein domain specific binding; protein-macromolecule adaptor activity
Biological process: negative regulation of transcription by RNA polymerase II; positive regulation of apoptotic process; spliceosomal snRNP assembly; RNA processing; spliceosomal tri-snRNP complex assembly; negative regulation of cell population proliferation; negative regulation of DNA-templated transcription
Cellular component: cytosol; membrane; nuclear body; nucleoplasm; SMN complex; SMN-Sm protein complex; cytoplasm; cytoskeleton; nucleus; Gemini of Cajal bodies; protein-containing complex; RNA polymerase II transcription repressor complex; transcription repressor complex
Genetic constraint (gnomAD): Loss-of-function variants: 59 observed, 75.96 expected, observed/expected ratio (o/e) 0.78, 90% interval 0.63 to 0.96. The upper end of that interval is the gene's LOEUF score, 0.96, which puts it in group 4 of 6, group 1 being the genes least tolerant of losing a copy. Missense variants: 976 observed, 1,019 expected, observed/expected ratio (o/e) 0.96, 90% interval 0.91 to 1.01. Synonymous variants: 357 observed, 358.07 expected, observed/expected ratio (o/e) 1, 90% interval 0.91 to 1.09.
Homologues: Orthologues: chimpanzee DDX20 (99% identical), macaque DDX20 (96% identical), rabbit DDX20 (89% identical), dog DDX20 (86% identical), pig DDX20 (85% identical), rat Ddx20 (84% identical), guinea pig DDX20 (83% identical), mouse Ddx20 (83% identical), tropical clawed frog ddx20 (52% identical), zebrafish ddx20 (48% identical), Caenorhabditis elegans mel-46 (26% identical), Drosophila melanogaster Gem3 (24% identical). Paralogues in human: EIF4A2 (16% identical), DDX42 (16% identical), DDX54 (16% identical), EIF4A1 (16% identical), DDX19B (16% identical), DDX39B (16% identical), DDX19A (16% identical), DDX10 (15% identical), DDX3X (15% identical), DDX6 (15% identical), EIF4A3 (15% identical), DDX3Y (15% identical), and 26 more.
Diseases named in the same sentence as DDX20 in open-access papers:
DDX20 is named in the same sentence as 42 diseases in open-access papers, as found by Europe PMC text mining. Sharing a sentence is not in itself a finding about the gene and the disease. The quoted sentences say what the papers report.
breast carcinoma (6 papers, 2021 to 2023). "Beyond its roles in breast cancer, prostate cancer, and hepatocellular carcinoma, DDX20 has been implicated in several other tumors." (PMID 37894677, 2023). "In breast cancer, DDX20 is involved in cell signaling pathway activity, which is a key factor in tumorigenesis." (PMID 37894677, 2023). "In contrast to its role in prostate and breast cancers, DDX20 acts as a tumor suppressor in liver cancer and suppresses tumorigenesis." (PMID 37894677, 2023). "In conclusion, DDX20 plays a role in the regulation of hepatocellular carcinoma development through various miRNAs, including miRNA-140-3P and miRNA-22, as well as in breast cancer development through miRNA-222." (PMID 37894677, 2023). "Cancer-specific antigens, DDX43 (helicase antigen gene, HAGE) and DDX53 (cancer-associated gene, CAGE), are overexpressed in almost all cancers, while DDX20 (dp103) is highly expressed in breast cancer." (PMID 36761420, 2022). "On the other hand, ectopic expression of DDX20/DP103 has been shown to enhance invasive abilities of breast cancer cells." (PMID 34708244, 2022). "To date, the aberrantly activated DDX20 has been reported to be correlated with invasiveness and metastatic behavior in multiple tumors, including prostate cancer, breast cancer, and oral squamous cell carcinoma." (PMID 36246406, 2022). "A deregulated DDX20 activity has been reported correlated with aggressive behaviour and metastatic potential in several tumours, including prostate cancer, hepatocellular carcinoma and breast cancers." (PMID 34290392, 2021). "In addition, DDX20 may exhibit an miRNA-processing role in breast cancer." (PMID 37894677, 2023). "A group of studies reported that DDX20 exhibited a negative correlation with an miRNA, namely miR-222, suggesting that DDX20 affects the NF-κB activity through miR-222 to promote breast cancer development." (PMID 37894677, 2023).
hepatocellular carcinoma (5 papers, 2017 to 2023). A malignant tumor that arises from hepatocytes. "Elevated DDX20 levels inhibit hepatocellular carcinoma cell migration and invasion by regulating the NF-κB signaling pathway." (PMID 37894677, 2023). "As reported, tumor genomics of RNAi performed in a mouse model of hepatocellular carcinoma has identified DDX20 as a tumor suppressor." (PMID 37894677, 2023). "Furthermore, DDX20 is significantly overexpressed in certain cancerous tissues, such as hepatocellular carcinoma and colorectal, prostate, and gastric cancers, and usually indicates a good prognosis." (PMID 37894677, 2023). "MiRNA-140-3p and miRNA-22, as miRNA, can inhibit NF-κ B activity, and DDX20 deletion in hepatocellular carcinoma (HCC) impaired this inhibitory effect of miRNA-140-3p and miRNA-22." (PMID 37894677, 2023).
bladder cancer (4 papers, 2010 to 2023). "Compared with that in the control group, WDR4 overexpression promoted the metastasis and proliferation of cancer cells, but simultaneously silencing DDX20 partially reversed the increases in the metastasis and proliferation of bladder cancer cells caused by WDR4 upregulation." (PMID 37783676, 2023). "The results revealed that the expression of either WDR4 or DDX20, similar to the correlations with T stage, was an independent predictor of LN metastasis in bladder cancer." (PMID 37783676, 2023). "To investigate the clinical significance of WDR4 and DDX20, we assembled a cohort of 77 bladder cancer tissues and 30 normal adjacent tissues." (PMID 37783676, 2023). "Our results also demonstrated that DDX20 promoted the metastasis and proliferation of bladder cancer cells." (PMID 37783676, 2023). "To determine whether DDX20 contributes to bladder cancer cell metastasis and proliferation, we knocked down DDX20 in UM-UC-3 cells." (PMID 37783676, 2023). "Subsequently, we studied the cooperative role of WDR4 and DDX20 in bladder cancer cells." (PMID 37783676, 2023). "Moreover, the CUT&Tag results showed that DDX20 binds to many gene transcriptional regulatory regions in bladder cancer cells." (PMID 37783676, 2023). "DDX20 rs197412 T variant was also found consistently associated with overall survival in patients with RCC and non-Hodgkin’s lymphoma (NHL), recurrence-free survival in bladder cancer, and both overall survival and progression-free survival in patients with esophageal adenocarcinoma." (PMID 36011315, 2022). "As an adaptor, WDR4 binds DDX20 and represses the transcription factor Egr1, thereby inhibiting the transcriptional expression of ARRB2 and ultimately promoting the progression of bladder cancer." (PMID 37783676, 2023). "Thus, WDR4 may interact with DDX20 in the nucleus to promote the progression of bladder cancer." (PMID 37783676, 2023). "The results of mechanistic studies suggested that WDR4 can recruit DEAD-box helicase 20 (DDX20) into the nucleus and inhibit the transcriptional expression of arrestin beta 2 (ARRB2), thus promoting LN metastasis and progression of bladder cancer." (PMID 37783676, 2023). "In addition, bladder cancer tissues of patients with LN metastasis displayed markedly higher WDR4 and DDX20 levels than those without LN metastasis." (PMID 37783676, 2023).
colon cancer (3 papers, 2021 to 2022). "In the current study, we investigated the potential association of DDX20 rs197412 polymorphism with colon cancer susceptibility and progression." (PMID 36011315, 2022). "Therefore, in the current study, we evaluated the association of the most common genetic polymorphism (rs197412: T/C) in the DDX20 gene with the risk and prognosis of colon cancer and uncovered its putative regulatory mechanism." (PMID 36011315, 2022). "DDX20 protein was localized in the nucleoplasm, nuclear bodies, and cytosol, with intense staining in colon cancer tissues." (PMID 36011315, 2022). "In the present study, DDX20 rs197412 was an independent prognostic marker for colon cancer recurrence-free survival." (PMID 36011315, 2022). "Here, we aimed to unravel the association of DDX20 rs197412 T/C variant with colon cancer risk and/or prognosis in paired samples of 122 colon cancer and non-cancer tissue specimens by TaqMan allelic discrimination analysis." (PMID 36011315, 2022).
colorectal cancer (3 papers, 2017 to 2023). A primary or metastatic malignant neoplasm that affects the colon or rectum. "DDX20 levels were also increased in prostate and colorectal cancers with distant metastases." (PMID 37783676, 2023). "A systematic search for DDX20 rs197412 yielded six colorectal cancer and 12 non-cancer articles." (PMID 36011315, 2022).
liver cancer (3 papers, 2022). An epithelial or non-epithelial malignant neoplasm that arises from the liver. "In addition, we investigated the association between the DDX20 expression level and OS of a liver cancer patients in six subgroups." (PMID 36246406, 2022). "In our analysis, liver cancer cell lines were highly dependent on DDX20 (dependency score range −0.636 to −1.336)." (PMID 36246406, 2022). "Overall, our study highlighted the tumor immunology role of DDX20 in liver cancer and provided a series of novel insights into DDX20 in liver cancer." (PMID 36246406, 2022). "UALCAN analysis of DNA methylation provided us a piece of important information regarding the DDX20 methylation level of liver cancer patients with different clinical features." (PMID 36246406, 2022). "In summary, DNA gene promoter methylation might contribute to the abnormal upregulation of DDX20 in liver cancer." (PMID 36246406, 2022). "Furthermore, we also detected a consistent trend that DDX20 was up-regulated in 40 liver cancer tissues from patients in our hospital." (PMID 36246406, 2022). "DAPK1 can inhibit the invasion and migration of liver cancer cells by up-regulating DDX20." (PMID 36290392, 2022). "In summary, our study revealed that DDX20 was aberrantly overexpressed in liver cancer." (PMID 36246406, 2022). "Overall, DDX20 might promote the proliferation and migration of oncogenic characteristics in liver cancer cells." (PMID 36246406, 2022). "In addition, we identified DDX20 as an essential gene for EGFR in the liver cancer cells." (PMID 36246406, 2022). "Moreover, reports of the GO and KEGG analysis demonstrated that signal release pathways, the neuroactive ligand-receptor interaction pathway, metal ion transmembrane transporter activity, and ion channel complex were significantly related to DDX20 upregulated in liver cancer." (PMID 36246406, 2022). "Our previous study has indicated that DAPK1 and DDX20 (DEAD-box helicase 20) can suppress liver cancer cell invasion and migration, and the role of DAPK1 on the function of liver cancer depends on DDX20." (PMID 36290392, 2022). "Patients with liver cancer in our trails all have hepatitis B virus infection, thereby limiting knowledge of potential relationships between nonneoplastic liver diseases and DDX20 expression." (PMID 36246406, 2022). "According to above results, the DDX20 may be a potential predicted biomarker and EGFR target gene for liver cancer." (PMID 36246406, 2022). "However, no studies have yet characterized the tumor biology of DDX20 in liver cancer." (PMID 36246406, 2022).
oral squamous cell carcinoma (3 papers, 2021 to 2022). "Moreover, combination of DDX20/DP103 along with Amphiregulin and Cyclin A1 has been correlated with aggressive forms of oral squamous cell carcinoma with up-regulated EMT-associated gene signature." (PMID 34708244, 2022).
colon adenocarcinoma (1 paper, 2022). "Mutations of SKIDA1, CLK1, NSFL1C, OR2A5, EDEM3, and OR51V1 were associated with significant deregulation of DDX20 gene expression pattern in colon adenocarcinoma patients." (PMID 36011315, 2022). "The DDX20 gene was significantly overexpressed in colon adenocarcinoma patients compared to controls." (PMID 36011315, 2022).
gastric cancer (1 paper, 2022). A primary or metastatic malignant neoplasm involving the stomach. "Compared with TIDE, T.Clonality, and B.Clonality, DDX20 alone had a higher AUC (0.71) in gastric cancer (Kim2018_PD1_Gastric)." (PMID 36246406, 2022).
glioma (1 paper, 2022). A benign or malignant brain and spinal cord tumor that arises from glial cells (astrocytes, oligodendrocytes, ependymal cells).
head and neck carcinoma (1 paper, 2021). A carcinoma that arises from the head and neck region. "Interestingly, the corresponding proteins CCNA1, AREG or DDX20 have been individually found involved in a large range of solid tumours, including head and neck carcinoma." (PMID 34290392, 2021).
head and neck squamous cell carcinoma (1 paper, 2022). A squamous cell carcinoma that arises from any of the following anatomic sites: lip and oral cavity, nasal cavity, paranasal sinuses, pharynx, larynx, and salivary glands. "Compared with TIDE, MIS score, CD274, CD8, IFNG, and Merck18, DDX20 alone had a higher AUC (0.71) in head and neck squamous cell carcinoma (Uppaluri2020_PD1_HNSC_Pre)." (PMID 36246406, 2022). "Compared with TIDE, MIS score, CD8, IFNG, and Merck18, DDX20 alone had a higher AUC (0.62) in head and neck squamous cell carcinoma (Uppaluri2020_PD1_HNSC_Post)." (PMID 36246406, 2022).
melanoma (1 paper, 2022). A malignant, usually aggressive tumor composed of atypical, neoplastic melanocytes. "Compared with TIDE, MSI score, CD274, CD8, IFNG, and Merck18, DDX20 alone had a higher AUC (0.68) in melanoma (Liu2019_PD1_Mealnoma_lip_Naive)." (PMID 36246406, 2022).
osteoarthritis (1 paper, 2024). A noninflammatory degenerative joint disease occurring chiefly in older persons, characterized by degeneration of the articular cartilage, hypertrophy of bone at the margins and changes in the synovial membrane. "A specific exosomal miRNA, miR-361-5p, demonstrates its efficacy in alleviating osteoarthritis by targeting DDX20 and deactivating the NF-κB signaling pathway." (PMID 37728585, 2024).
viral infection (1 paper, 2023). "Herein, we review the effects of DDX20 on the innate immune system and its role in transcriptional and post-transcriptional modification processes, based on which we provide an outlook on the future of DDX20 research in innate immunity and viral infections." (PMID 37894677, 2023). "Thus, although the role of DDX20 in suppressing viral infection and innate immunity has not been extensively studied, it has great research potential." (PMID 37894677, 2023). "In terms of changes in its expression upon viral infection, researchers reported that DDX20 is differentially expressed at distinct stages of human immunodeficiency virus type 1 (HIV-1) infection and found that DDX20 interacts with the HIV-1 coprotein Vpr as early as 2012." (PMID 37894677, 2023).
cancer (11 papers, 2016 to 2023). A tumor composed of atypical neoplastic, often pleomorphic cells that invade other tissues. "Variants of the DEAD-Box Helicase 20 (DDX20), one of the microRNAs (miRNAs) machinery genes, can modulate miRNA/target gene expressions and, hence, influence cancer susceptibility and prognosis." (PMID 36011315, 2022). "Genetic variations in DDX20 can potentially disrupt the fine-tune regulation of multiple biological cellular processes, leading to cancer development and susceptibility." (PMID 36011315, 2022). "The rs197412 SNP of DDX20 has been identified for its association with increased cancer susceptibility and outcomes." (PMID 36011315, 2022). "Aberrant expression and mutations of the DDX20 gene were associated with cancer development and progression." (PMID 36011315, 2022). "Somatic mutation of DDX20 in cancer tissues was significantly associated with recurrence." (PMID 36011315, 2022). "Unraveling the role of DDX20 in cancer may assist in the risk stratification of patients." (PMID 36011315, 2022). "For instance, alterations in DDX20 expression in cancer tissues can affect NF-κB activity, leading to cancer development." (PMID 37894677, 2023). "Staining of two tissue sections from the same patient with either an anti-WDR4 or an anti-DDX20 antibody showed increased regional WDR4 and DDX20 levels in cancer tissues and a positive correlation between WDR4 and DDX20 expression." (PMID 37783676, 2023). "Histological staining showed that WDR4 and DDX20 were both upregulated in cancer tissues compared with normal tissues." (PMID 37783676, 2023). "Mechanism of DDX20 in acting directly within cancer cells or tumor microenvironment still needed experiments for investigation." (PMID 36246406, 2022). "We were able to demonstrate that DDX20 is an important cancer-promoting molecule in liver tumors and exhibits a therapeutic target and tumor immune-suppressive features." (PMID 36246406, 2022). "Furthermore, increasing evidence suggests that DDX20 plays a crucial role in predicting the development, invasion, and drug response of cancer." (PMID 37894677, 2023). "Additionally, helicases such as DDX5, DDX20/DP103, and DHX9/DDX9 have also been implicated in cancer aggressiveness." (PMID 34708244, 2022). "Thus, the establishment of the DDX20–NF-κB–MMP9 axis could better reveal the mechanism by which DDX20 can promote cancer development." (PMID 37894677, 2023). "This suggests that DDX20 may play a role in promoting cancer metastasis." (PMID 37783676, 2023). "Thus, our finding suggested that targeted DDX20 may be a therapeutic strategy for controlling EGFR copy number heterogeneity in cancer." (PMID 36246406, 2022). "This connection between DDX20 and EBV led to the initial discovery of a link between DDX20 and cancer." (PMID 37894677, 2023).